RN7SKP47 (RN7SK pseudogene 47)
Gene: Miscellaneous RNA gene on chromosome 9 (74,799,895 to 74,800,222, forward strand). Ensembl gene ENSG00000202217.
Homologues: Orthologues: chimpanzee 7SK (99% identical), guinea pig 7SK (52% identical). Paralogues in human: RN7SKP176 (73% identical), 7SK (73% identical), RN7SKP71 (73% identical), RN7SKP79 (72% identical), RN7SKP189 (72% identical), RN7SKP124 (72% identical), RN7SKP200 (72% identical), RN7SKP133 (71% identical), RN7SKP243 (71% identical), RN7SKP255 (71% identical), RN7SKP78 (71% identical), RN7SKP153 (71% identical), and 284 more.